MIR525 (microRNA 525)
Synonyms: hsa-mir-525; MIRN525
Gene: MicroRNA gene on chromosome 19 (53,697,533 to 53,697,617, forward strand). Ensembl gene ENSG00000207711.
Gene Ontology:
Biological process: miRNA-mediated post-transcriptional gene silencing
Homologues: Orthologues: chimpanzee ptr-mir-525 (98% identical). Paralogues in human: MIR518C (85% identical), MIR518D (84% identical), MIR524 (84% identical), MIR518F (82% identical), MIR523 (82% identical), MIR516A1 (81% identical), MIR518E (81% identical), MIR521-1 (81% identical), MIR516A2 (80% identical), MIR516B1 (80% identical), MIR518B (80% identical), MIR520C (80% identical), and 12 more.